ANO6 (anoctamin 6)
Description:
Small-conductance calcium-activated nonselective cation (SCAN) channel which acts as a regulator of phospholipid scrambling in platelets and osteoblasts. Phospholipid scrambling results in surface exposure of phosphatidylserine which in platelets is essential to trigger the clotting system whereas in osteoblasts is essential for the deposition of hydroxyapatite during bone mineralization (By similarity). Has calcium-dependent phospholipid scramblase activity; scrambles phosphatidylserine, phosphatidylcholine and galactosylceramide (By similarity). Can generate outwardly rectifying chloride channel currents in airway epithelial cells and Jurkat T lymphocytes (By similarity). (Microbial infection) Upon SARS coronavirus-2/SARS-CoV-2 infection, is activated by spike protein which increases the amplitude of spontaneous Ca(2+) signals and is required for spike-mediated syncytia.
Synonyms: TMEM16F; DKFZp313M0720; BDPLT7; SCTS
Tractability: Antibody: UniProt places it where antibodies can reach, with high confidence; its Gene Ontology location is reachable by antibodies, with high confidence; UniProt predicts a signal peptide or a membrane-spanning region. PROTAC: ubiquitination databases record sites on it; its protein half-life has been measured.
Gene: Protein-coding gene on chromosome 12 (45,215,987 to 45,482,280, forward strand). Ensembl gene ENSG00000177119.
Subcellular location: Cell membrane
Subcellular location (Human Protein Atlas): Cytosol; Plasma membrane
Pathways (Reactome):
Disease: Defective ANO6 does not expose PS, PE on the platelet membrane; Induction of Cell-Cell Fusion
Hemostasis: Amplification and propagation of coagulation cascade; Regulation of clotting cascade
Immune System: Neutrophil degranulation
Transport of small molecules: Stimuli-sensing channels
Gene Ontology:
Molecular function: calcium-activated cation channel activity; intracellularly calcium-gated chloride channel activity; phospholipid scramblase activity; protein binding; voltage-gated chloride channel activity; chloride channel activity; voltage-gated monoatomic ion channel activity; identical protein binding; protein dimerization activity; protein homodimerization activity
Biological process: activation of blood coagulation via clotting cascade; bleb assembly; calcium ion transmembrane transport; chloride transmembrane transport; negative regulation of cell volume; phosphatidylserine exposure on blood platelet; plasma membrane phospholipid scrambling; pore complex assembly; positive regulation of bone mineralization; positive regulation of monoatomic ion transmembrane transport; positive regulation of monocyte chemotaxis; purinergic nucleotide receptor signaling pathway; sodium ion transmembrane transport; blood coagulation; calcium activated phosphatidylcholine scrambling; calcium activated phosphatidylserine scrambling; monoatomic ion transmembrane transport; positive regulation of apoptotic process; positive regulation of phagocytosis, engulfment; phospholipid translocation; positive regulation of potassium ion export across plasma membrane; regulation of postsynaptic membrane potential
Cellular component: cell surface; chloride channel complex; extracellular exosome; membrane; plasma membrane; specific granule membrane; tertiary granule membrane; cholinergic synapse; synaptic membrane
Genetic constraint (gnomAD): Loss-of-function variants: 103 observed, 118.99 expected, observed/expected ratio (o/e) 0.87, 90% interval 0.74 to 1.02. The upper end of that interval is the gene's LOEUF score, 1.02, which puts it in group 4 of 6, group 1 being the genes least tolerant of losing a copy. Missense variants: 954 observed, 1,181.1 expected, observed/expected ratio (o/e) 0.81, 90% interval 0.76 to 0.85. Synonymous variants: 367 observed, 406.3 expected, observed/expected ratio (o/e) 0.9, 90% interval 0.83 to 0.99.
Gene-disease validity (ClinGen):
ClinGen rates the evidence that ANO6 causes each of these diseases.
Scott syndrome (autosomal recessive): Moderate. Scott syndrome is an extremely rare congenital hemorrhagic disorder characterized by hemorrhagic episodes due to impaired platelet coagulant activity.
Homologues: Orthologues: chimpanzee ANO6 (99% identical), macaque ANO6 (97% identical), rabbit ANO6 (91% identical), rat Ano6 (91% identical), mouse Ano6 (90% identical), pig ANO6 (90% identical), dog ANO6 (89% identical), guinea pig ANO6 (88% identical), tropical clawed frog ano6 (73% identical), zebrafish ano6 (61% identical). Paralogues in human: ANO5 (48% identical), ANO4 (42% identical), ANO3 (41% identical), ANO1 (37% identical), ANO2 (35% identical), ANO7 (34% identical), ANO9 (27% identical), ANO8 (22% identical), ANO10 (20% identical), PPP1R7 (9% identical).
Diseases named in the same sentence as ANO6 in open-access papers:
ANO6 is named in the same sentence as 80 diseases in open-access papers, as found by Europe PMC text mining. Sharing a sentence is not in itself a finding about the gene and the disease. The quoted sentences say what the papers report.
Scott syndrome (33 papers, 2013 to 2025). "Investigation revealed that TMEM16F (Ano6) a Ca2+-activated Cl− channel that also exhibits PL scrambling in plasma membrane exhibits a homozygous null mutation in Scott Syndrome patients." (PMID 35422844, 2022). "Loss of function mutations in ANO6 of hematopoietic cells lead to Scott syndrome, a rare bleeding disorder." (PMID 30753537, 2019). "A mutation of Ano6 that truncates the ANO6 protein is associated with a rare bleeding disorder, the Scott syndrome." (PMID 26811235, 2016). "ANO2 is involved in olfaction, whereas ANO6 works as a scramblase whose mutation causes a rare bleeding disorder, the Scott syndrome." (PMID 26811235, 2016). "Recent findings however question if a deficiency of anoctamin-6 alone can account for the complex phenotype of Scott syndrome platelets." (PMID 27535140, 2016). "The Scott syndrome is a very rare and likely underdiagnosed bleeding disorder associated with mutations in the gene encoding anoctamin-6." (PMID 27535140, 2016). "A role of anoctamin-6 in Scott syndrome was postulated by the discovery of dysfunctional mutations in the ANO6 gene of two unrelated patients." (PMID 27535140, 2016). "To confirm the complex altered phenotype of Scott platelets, we analyzed whole blood and isolated platelets from a Scott syndrome patient with two likely disruptive mutations in the anoctamin-6 alleles." (PMID 27535140, 2016). "The Scott syndrome patient was found to have a splice site mutation in TMEM16F, now known as anoctamin 6 (ANO6)." (PMID 24987374, 2014). "Indeed, mutations in ANO6 have been identified in patients with Scott syndrome, a rare genetic bleeding disorder caused by a defect in PS scrambling in platelets." (PMID 24663380, 2014). "Additionally, Ano5, has been implicated in muscle and bone diseases, Ano6 is important for innate immunity, and mutations in Ano6 cause Scott Syndrome (a bleeding disorder), while Ano10 may play a role in macrophage volume regulation." (PMID 29579047, 2018). "Along with ANO5, which has been connected to specific types of muscular dystrophy, ANO6 and ANO10 have also been linked to Scott syndrome and autosomal recessive spinocerebellar ataxia, respectively." (PMID 36836529, 2023). "Anoctamin 6 (Ano6) is required for Ca2+-dependent phosphatidylserine exposure and is defective in patients with Scott syndrome, a rare bleeding disorder." (PMID 24357800, 2013). "The purpose of our study is to report the case of a parturient woman with Scott ́s syndrome secondary to a mutation of the ANO6 gene never described in the literature." (PMID 37455884, 2023). "As our PFD cohort had normal ANO6 transcript levels, anoctamin 6 abnormalities could be highly specific for Scott's syndrome." (PMID 34185390, 2021). "Calcium-dependent ADAM10 activation could not be induced in lymphocytes of patients with Scott syndrome harbouring a missense mutation in ANO6." (PMID 30753537, 2019). "Both phosphatidylserine exposure and ballooning are absent in activated platelets from Scott syndrome patients, lacking the Ca2+-activated channel protein anoctamin-6 (gene ANO6 or TMEM16F), as well as in activated platelets from Ano6 deficient mice." (PMID 33490118, 2020).
breast cancer (15 papers, 2021 to 2025). A primary or metastatic malignant neoplasm involving the breast. "The results of the analysis reported here highlight the significant association between ANO6 and breast cancer risk as well as its strong correlation with disease outcomes." (PMID 40696618, 2025). "ANO6 was also associated with metastatic capability of mammary cancers in mice and was related to poor prognosis of patients with breast cancer." (PMID 36793597, 2023). "A previous study demonstrated that ANO6 is associated with the metastatic potential of breast cancer." (PMID 36467500, 2022). "The risk score of breast cancer prognosis was determined with the following formula: RiskScore = 0.629*ANO6 + 0.147*CELSR3 + 0.381*CLDN7+ 0.273*EPB41L4B-0.357*FAM166B -0.843*GPLD1–0.202*LEF1–0.202*PPARG -0.127*SUSD3." (PMID 34364397, 2021). "In conclusion, the developed prognostic risk model effectively predicts survival outcomes in patients with breast cancer, with ANO6 and PLGRKT being pivotal in tumor progression." (PMID 40762681, 2025). "Our experiments showed that increased ANO6 expression impedes the invasion and metastasis of breast cancer cells, thus significantly influencing disease progression." (PMID 40696618, 2025). "Through experimental validation, we found that excessive expression of ANO6 profoundly impedes the migration of breast cancer cells." (PMID 40696618, 2025). "Three ion channel genes KCNK1, CLCN3, and CACNB3, which were overexpressed in breast cancer, and another ion channel gene ANO6, which was underexpressed in breast cancer, were identified by significance analysis of microarrays (SAM)." (PMID 38905316, 2024). "Relationship between ANO6 levels and clinicopathological parameters of breast cancer patients." (PMID 37960776, 2023). "Cox regression analysis of ANO6 and other clinical parameters for breast cancer." (PMID 37960776, 2023). "Moreover, anoctamin 6 overexpression inhibited breast cancer cell invasion and metastasis." (PMID 40696618, 2025). "The hindrance of breast cancer invasion and metastasis – and, consequently, a slowing of disease progression and improved outcomes for the patient – may be possible with treatments based on overexpression of ANO6." (PMID 40696618, 2025). "By systematically integrating efferocytosis- and invasion-related genes, this study identified ANO6 and PLGRKT as dual-process-driven prognostic biomarkers in breast cancer." (PMID 40762681, 2025). "The results indicated that EMC2, G6PD, FLT3, IFNG, ANO6, and SLC1A4 were positively correlated with ferroptosis while CISD1, TP63, and BRD4 were negatively correlated with ferroptosis in breast cancer." (PMID 34222241, 2021). "In contrast, the expression of CLCN3, CACNB3, and ANO6 in breast cancer did not correlate significantly with patient prognosis." (PMID 38905316, 2024). "The antagonistic risk weights of ANO6 (positive coefficient) and PLGRKT (negative coefficient) reflect their potential functional interplay in balancing tumor microenvironment dynamics, providing a novel molecular lens for deciphering breast cancer heterogeneity." (PMID 40762681, 2025).
bleeding disorder (14 papers, 2013 to 2025). "Moreover, ANO6 is involved in the pathogenesis of many diseases, such as cancer, hemorrhagic disease, and bone dysplasia." (PMID 35558081, 2022). "The significance of ANO6 has also been found in bleeding disorders and bone dysplasia." (PMID 34364397, 2021).
glioma (7 papers, 2021 to 2025). A benign or malignant brain and spinal cord tumor that arises from glial cells (astrocytes, oligodendrocytes, ependymal cells). "In glioma, high expression of ANO6 is associated with a lower survival rate suggesting that differential expression of ANO6 can be used as an independent prognostic factor in BC." (PMID 35558081, 2022). "A recent study showed that ANO6 is increased in human glioma tissue and that high ANO6 expression is associated with worsened survival." (PMID 36497413, 2022). "In glioma, ANO6 induces cancer cell proliferation and invasion by regulating the ERK signaling pathway." (PMID 38238671, 2024). "ANO6 has a higher expression in gliomas, and inhibition ANO6 suppresses the proliferation and invasion of gliomas cells." (PMID 34364397, 2021). "Furthermore, ANO6 knockdown reduces glioma cell viability, proliferation, and invasion by inhibiting ERK signalling." (PMID 36497413, 2022). "However, it remains unclear whether ANO6 regulates glioma cell progression via ion current activity, scramblase activity, or a combination of these effects in synergy with other ANO proteins such as ANO1." (PMID 36497413, 2022).
cyst (2 papers, 2015 to 2025). A sac-like closed membranous structure that may be empty or contain fluid or amorphous material. "Next, we were interested to determine the mechanisms underlying the increased number of cells within the cyst lumen in ANO6-deficient cells." (PMID 26448322, 2015). "In accordance with our previous findings, the lumen-to-cyst ratio was augmented in the presence of forskolin in both ANO6-competent and ANO6-deficient cells, again reflecting preserved lumen expansion owing to transepithelial chloride secretion." (PMID 26448322, 2015). "ANO6 was found in our dataset, and is a known regulator of cyst lumen formation in ADPKD, and was thus utilized here as a control." (PMID 41086943, 2025). "This study was conducted to determine the subcellular localization of ANO6 in renal tubular cells and a possible role of this protein in cyst formation." (PMID 26448322, 2015). "In addition, we show that ANO6 is involved in cyst formation by mediating apoptosis-dependent cavitation, a prerequisite for proper lumen formation." (PMID 26448322, 2015). "However, knockdown of ANO6 impaired cyst lumen formation of MDCK cells in three-dimensional culture." (PMID 26448322, 2015). "In addition, ANO6 was highly expressed in rounded apoptotic epithelial cells characterized by strong expression of the pro-apoptotic protein BNIP3, supporting the hypothesis of a functional role of ANO6 in apoptosis of cyst-lining epithelial cells." (PMID 26448322, 2015). "This suggests that ANO6 is not essential for fluid secretion into the cyst lumen, the main mechanism of cyst expansion, although forskolin led to a significant translocation of ANO6 from the cytosol towards the apical membrane." (PMID 26448322, 2015).
Hypertension (2 papers, 2020 to 2023). The presence of chronic increased pressure in the systemic arterial system. "ANO6, CXCR4, and HIF1A were significant also after adjustment for baseline variables showing an imbalance between STEMI and NSTEMI groups (age, hypercholesterolemia, hypertension, aspirin and statin use, time-to-presentation, admission cTnI)." (PMID 32457432, 2020).
Listeria infection (2 papers, 2024 to 2025). "For instance, a recent study revealed that Ca2+-activated lipid scramblase TMEM16F (also known as anoctamin 6; ANO6), regulates lipid metabolism to suppress excessive inflammation during Listeria monocytogenes infection." (PMID 40568596, 2025).
polycystic kidneys (2 papers, 2015 to 2023). "Further in vivo analyses will be required to confirm a functional role of ANO6 in polycystic kidney disease." (PMID 26448322, 2015). "Finally, polycystic kidneys are under constant oxidative stress, which causes lipid peroxidation and the activation of ANO1 and ANO6." (PMID 37686084, 2023).
aneurysm (1 paper, 2025). Bulging or ballooning in an area of an artery secondary to arterial wall weakening. "Additionally, transcriptome data reveal that CACNA2D3 is markedly upregulated in the walls of ruptured IAs, whereas ANO6 exhibits significantly higher expression in unruptured aneurysm walls." (PMID 40388745, 2025).
cervical squamous cell carcinoma (1 paper, 2024). A squamous cell carcinoma arising from the cervical epithelium. "Meanwhile, SLC2A1, ANO6, and TXNIP are associated with cervical squamous cell carcinoma and may be ferroptosis‐related markers of this disease." (PMID 39526479, 2024). "SLC2A1, ANO6, and TXNIP are associated with cervical squamous cell carcinoma and may serve as ferroptosis‐related markers of the disease." (PMID 39526479, 2024). "SLC2A1, ANO6, and TXNIP are associated with cervical squamous cell carcinoma and may be ferroptosis‐related markers of the disease." (PMID 39526479, 2024). "Interestingly, TXNIP exhibited a positive correlation with the survival rate and prognosis of patients with cervical squamous cell carcinoma, whereas ANO6 and SLC2A1 showed the opposite trend; both genes were negatively correlated with the survival rate and prognosis of patients." (PMID 39526479, 2024).
gastrointestinal stromal tumor (1 paper, 2024). "Herein, we elucidate the potential role of ANO6 (TMEM16F) in gastrointestinal stromal tumors (GISTs)." (PMID 38756246, 2024).
inflammatory bowel disease (1 paper, 2013). A spectrum of small and large bowel inflammatory diseases of unknown etiology. "However, a significant association between ANO6 polymorphism rs17095830 and inflammatory bowel disease (IBD) was found even after Bonferroni correction." (PMID 23308121, 2013). "However, a significant association between ANO6 polymorphism rs17095830 and inflammatory bowel disease (IBD) was observed." (PMID 23308121, 2013).
intracranial aneurysm (1 paper, 2025). "Transcriptome data from intracranial aneurysm samples confirmed significant differential expression of CACNA2D3 and ANO6 between ruptured and unruptured groups." (PMID 40388745, 2025).
lung carcinoma (1 paper, 2023). "However, the role of ANO6 in lung cancer has not been illustrated." (PMID 36793597, 2023).
major depressive disorder (1 paper, 2014). An episode of depression lasting two or more weeks without an intervening episode of mania. "ANO2 and ANO6 are associated with panic disorder and major depressive disorder, respectively." (PMID 24473445, 2014).
mastitis (1 paper, 2026). Inflammation of breast tissue during lactation or postpartum due to an obstructed duct or infection. "Collectively, these findings suggest that the BMNCR/miR-145/ANO6 axis is involved in the regulation of inflammatory responses and epithelial homeostasis during bovine mastitis, with BMNCR functioning as a protective regulator in this process." (PMID 42193737, 2026).
Obesity (1 paper, 2022). Accumulation of substantial excess body fat. "For the identified DEHGs for obesity, there were six previously reported genes (UGGT1, ANO6, MPEG1, PTGS1, CLU and IQGAP1) and two novel genes (LUZP6 and PLCB2) for obesity." (PMID 35568907, 2022).
uveal melanoma (1 paper, 2021). A melanoma derived from melanocytes of the uveal tract. "After knockdown of ANO6 gene, the in MUM2B cell lines showed a significant decrease in nuclear DNA synthesis, indicating the ANO6 gene may progress the proliferation of uveal melanoma cell lines, which sheds light on further study." (PMID 34901006, 2021). "5-ethynyl-2 deoxyuridine (EdU) assay was performed to test whether the knockdown of gene ANO6 could influence uveal melanoma cell proliferation in vitro." (PMID 34901006, 2021).